CD40 (CD40 molecule)
Diseases named in the same sentence as CD40 in open-access papers (continued):
Sharing a sentence is not in itself a finding about the gene and the disease.
cancer (389 papers, 2003 to 2026). A tumor composed of atypical neoplastic, often pleomorphic cells that invade other tissues. "Current research is now focused on strategies to overcome stromal barriers and to “reprogram” or deplete immunosuppressive cell populations within the TME, such as using CD40 agonists, CSF-1R inhibitors, or therapies targeting cancer-associated fibroblasts." (PMID 41331510, 2025). "Our analysis also highlights that T cells, (re-)activated through immune checkpoint blockade therapy, can effectively target CD40+ cancer cells, exploiting their CD40 susceptibility." (PMID 40397730, 2025). "CD6 serves as a therapeutic target in cancer immunotherapy, while CD40 is associated with the severity of COPD and the degree of pulmonary function alteration." (PMID 39206312, 2024). "It is thought that the effect of susceptibility to cancer is made by altering the level of CD40 protein." (PMID 39625893, 2024). "The CD40 (rs1883832) polymorphism located on chromosome 20 has been linked to an increased vulnerability to certain types of cancer." (PMID 39625893, 2024). "Among the downregulated DEGs, PLEKHA5, GRK4, MYRIP, and CD40 have established associations with various human cancers." (PMID 39911484, 2024). "In carcinoma cells, CD40 recruits TNFR-associated factor (TRAF) proteins (such as TRAF3) to activate pro-apoptotic ASK-1 and facilitate activation of the NOX complex to induce ROS production." (PMID 36291141, 2022). "Among all the significant associations, CD36 expression was positively correlated with CD27, CD28, CD40, and ICOS in multiple cancer types, but negatively associated with CD40 in TGCA." (PMID 34234847, 2021). "Consistently, high CD40 expression in tumors is associated with a better survival of cancer patients (log-rank test, p = 0.003)." (PMID 34758832, 2021). "In conclusion, the combination of MEK inhibitor GDC-0623 and agonist anti-CD40 Ab is a highly potent regimen for the treatment of tumors, especially for cancers such as PDA that are driven by mutated KRAS and heavily infiltrated by myeloid cells." (PMID 32358491, 2020). "CD40 deficiency in the blood compartment attenuated experimental lung metastasis, indicating a potential involvement of platelet CD40 in cancer progression." (PMID 31552050, 2019). "Cytoplasmic and membranous CD40 expression in carcinoma cells was positively associated with expression in CAFs (both p < 0.001)." (PMID 31137630, 2019). "Combination of CpG-ODNs with other therapies, such as anti-CD40 exhibited promising results associated with the repolarization of TAMs, even in poorly immunogenic cancer models such as a preclinical glioma model." (PMID 28769933, 2017). "In our recent studies, we have further demonstrated the proof of concept that strongly support the clinical development of CD40-targeting therapeutic vaccines for HPV16-associated cancers using our prototype vaccine, anti-CD40-HPV16.E6/7 protein." (PMID 28133621, 2016). "Membrane-bound CD40L (mCD40L) but not soluble CD40L (sCD40L) has been implicated in direct cell death induction and apoptosis in CD40-expressing carcinomas." (PMID 26986513, 2016). "The incubation with CD40L leads to the apoptosis of transformed cells, whereas decreased expression of CD40 on these cells is associated with enhanced cancer progression." (PMID 25117071, 2014). "We have generated an E1-, E3- deleted replication deficient adenovirus expressing CD40L and shown that CD40-positive carcinoma cell lines are sensitive to CD40L-induced cell death." (PMID 20211016, 2010). "GSEA results indicated that patients whose tumors showed decreased expression of the genes associated with the CD40 signaling pathway were more likely to have residual cancer after trastuzumab-plus-T/FEC chemotherapy." (PMID 18086299, 2007).
cancer (continued). "Results of gene set enrichment analysis suggested that the lower expression of genes involved with CD40 signaling is associated with a greater risk of residual cancer after the preoperative chemotherapy that includes trastuzumab." (PMID 18086299, 2007). "Hyperactive WNT/β-catenin signaling, often driven by APC loss, is a well-established pan-cancer mechanism for fostering an immune-excluded microenvironment by preventing T-cell infiltration, providing a mechanistic basis for the observed low CD40 expression." (PMID 41182434, 2025). "Additionally, CD40 can be present on exosomes; its role on these vesicles has been linked to cancer." (PMID 40003965, 2025). "Cancer susceptibility is believed to be exerted by altering the levels of the CD40 protein." (PMID 39625893, 2024). "Moreover, the CD40 pathway is associated with several diseases, including cancer, where the interaction between CD40 and CD40L is pleiotropic and context-dependent." (PMID 37970926, 2023). "CD40 is a member of the tumour necrosis factor family expressed by immune cells, and its elevated expression and activity have been linked with different malignancies, including cancer." (PMID 28640192, 2017). "Moreover, various cancer cell lines exhibit a varied level of CD40, which is associated with cancer stage and usually decreases with disease progression." (PMID 25117071, 2014). "In leukemic cells, signaling via CD40 has been linked to both pro-survival and anti-cancer effects." (PMID 24741998, 2014). "Furthermore, adenoviral cancer vaccines encoding TAAs targeted to CD40 on DCs are currently in development." (PMID 24664420, 2014). "In multivariable analysis, high CD40 RNA expression was significantly associated with liver and bile duct (odds ratio [OR] 5.4, 95% confidence interval [CI] 1.9–15.0, P < 0.001), pancreatic (OR 4.5, 95% CI 2.3–8.8, P < 0.001), and ovarian (OR 4.4, 95% CI 2.1–9.2, P < 0.001) cancers." (PMID 41182434, 2025). "CD40 agonists, which are currently in clinical trials for various cancer types, including PDAC, promote APC upregulation of co-stimulatory molecules and cytokines that are essential for T-cell activation and proliferation." (PMID 40299790, 2025). "In cancer research, CD40-targeted therapy is capable of re-educating M2, demonstrating its ability to regulate macrophage polarization." (PMID 40746551, 2025). "Unlike CD4+ T cells, which operate under MHC-II restriction, CD8+ T cells can activate CD40 on virtually any cell, including cancer cells, upon recognizing specific peptide/MHC-I complexes with their T cell receptor (TCR)." (PMID 40397730, 2025). "In this study, the co-stimulating protein CD40 was significantly higher expressed on the surface of gas plasma-treated cancer cells than in untreated controls." (PMID 41345386, 2025). "Mechanistically, CD40L+CD8+ T cells can induce cell death in CD40-expressing cancer cells by triggering caspase-8 activation." (PMID 40397730, 2025). "Recent in vivo studies reveal that CD40 agonists exhibit remarkable efficacy in cancer immunotherapy, particularly when combined with immune checkpoint inhibitors." (PMID 41268556, 2025). "We conducted a pan-cancer transcriptome analysis of CD40, its ligand, and related immune markers to evaluate co-expression patterns and clinical outcomes." (PMID 41182434, 2025). "We demonstrate that a gene signature for resistance to CD40 signaling–induced cell death strongly correlates with worse survival in different human cancer cohorts." (PMID 40397730, 2025). "Both high CD40 and low–moderate CD40 ligand expression—potentially conducive to CD40 agonist therapy—was most frequent in ovarian (33%) and pancreatic (24%) cancer." (PMID 41182434, 2025). "This confirms our results obtained with TAg+ cells that CD40 signaling transmits an apoptotic signal in CD40tg TRAMP-C1 cancer cells." (PMID 40397730, 2025).
cancer (continued). "AKNA contains multiple PEST protein cleavage motifs that directly bind to A/T-rich regulatory elements of the promoter region of CD40 and CD40 that played an important role in carcinogenesis through the deregulation of the immune system in cancer." (PMID 39996799, 2025). "This study observed a comparable or even augmented CD40 expression in response to combination treatment with pPAMPs, suggesting an interaction between bacteria-derived PAMPs and cancer cell biology." (PMID 41345386, 2025). "CD40L expressed by activated CD8+ T cells interacts with CD40 on cancer cells and triggers cell death through caspase activation." (PMID 40397730, 2025). "Anti-cancer immunity was enhanced from immunomodulatory anti-CD40 monoclonal antibodies (mAbs) by substituting CD4 T-lymphocytes and CD40L in the activation process of APCs5." (PMID 40683864, 2025). "Multiple clinical evaluations of combination therapies with various CD40 agonists for different cancer types have been conducted." (PMID 41430039, 2025). "High CD40 expression was most frequent in liver and bile duct (42%), pancreatic (42%), and ovarian (40%) cancers." (PMID 41182434, 2025). "CD40 triggering on cancer cells activated caspase-8, the initiator caspase of extrinsic apoptosis, assessed by the cell-permeable fluorescent marker FITC-IETD-FMK." (PMID 40397730, 2025). "On the contrary, cytoplasmic CD40 expression was reported to be positively correlated with higher overall survival, although there was a higher ratio of positive cases in cancer cases in comparison with the normal tissue." (PMID 38638433, 2024). "Of interest, CD40‐positive cancers were recently shown to correlate to a better response to checkpoint blockade therapy." (PMID 38494863, 2024). "A potent activator of dendritic cells, CD40 agonism is a reasonable adjunct to multiple cancer therapies." (PMID 38903502, 2024). "As predicted, the administration of P21 to only DCs or cancer cells slightly enhanced DC maturation (CD11C+CD40+, CD80+, or CD86+) compared with the untreated group." (PMID 38994018, 2024). "The analysis of 46 immunostimulatory genes in pan-cancer showed that HSP90B1 expression was positively correlated with CD40, CD270, PVR, MICB, ULBP1, TNFSF4, while exhibiting a negative correlation with CD48 and CD40LG in most cancers." (PMID 38243263, 2024). "HER-2, CD155, CD40, and several other molecules are well-known proteins expressed on cancer cells and utilized as viral receptors for oncolytic virus binding and infection." (PMID 38178138, 2024). "In terms of cancer, CD40 expression is observed in 80% of NSCLC cases, 40% of ovarian cancer cases, and 68% of pancreatic adenocarcinoma cases in a recently published study." (PMID 38638433, 2024). "Current applications of CD40-directed cancer immunotherapy rely on the release of endogenous tumor antigen for T cell priming and activation." (PMID 39500897, 2024). "With the success in preclinical models, there are now multiple clinical trials testing CD40 agonism as monotherapy or in combination with other cancer therapies." (PMID 38903502, 2024). "CD40 agonists are performing well in preclinical cancer models, leading to ongoing clinical trials evaluating CD40 agonists alone and in combination with immune checkpoint inhibitors (NCT04495257)." (PMID 38785789, 2024). "Given that sotigalimab upregulated PD-L1 in the TME, the dual targeting of PD-1 or PD-L1 and CD40 with neoadjuvant chemoradiation in E/GEJ cancer is a rational strategy for future trials." (PMID 38181044, 2024). "CP-870,893, APX005M, and RO7009789 are agonistic anti-CD40 antibodies being tested in clinical trials for different types of cancers." (PMID 39003350, 2024). "To address this question, we exposed macrophages co-cultured with cancer cells under 2D conditions, to CSF1Ri and anti-CD40 mAb." (PMID 37346794, 2023).
cancer (continued). "Ultimately, however, Cxcr3 was critical for mitigating cancer cell dissemination following immunotherapy with CD40 agonist + anti-PD-L1 or T cell receptor engineered T cell therapy targeting mesothelin." (PMID 36472588, 2023). "From these observations, we concluded that long-term combined treatment of MTS diminished both cancer cell viability and cancer cell proliferation at > 0.5 μM of CSF1Ri - anti-CD40 mAb." (PMID 37346794, 2023). "In contrast, cancer cells from MTS exposed to combined anti-CD40 mAb and CSF1Ri treatments showed a significant reduction in viability and G2/M cell cycle progression." (PMID 37346794, 2023). "Interactions between CD40L and its counter-receptor CD40 have been found to have a fundamental role in inflammation and development of adaptive immunity against infections and cancer, predominantly in the effector phase of the immune response." (PMID 37958563, 2023). "CD40 agonists have, therefore, been of interest to develop as candidates for adjuvants or cancer immunotherapy." (PMID 37353664, 2023). "Generally, agonistic CD40 antibodies have a minimal response rate in cancer patients, except for selicrelumab." (PMID 38008741, 2023). "Previous studies have shown that the antitumor effect of CD40 agonist antibody is T cell-dependent and induction of immune memory is essential to prevent cancer recurrence." (PMID 37291146, 2023). "In summary, both agonistic CD40 therapies and cancer vaccines are in the early stages of clinical development and show promise, in particular in combination with other immunotherapies to overcome immunosuppression." (PMID 37240052, 2023). "These hemorrhage-derived TAMs drive cancer growth, tissue invasion, and resistance to CD40-agonistic immunotherapy." (PMID 38060331, 2023). "For most types of cancers with low immunogenicity, it is hard to effectively destroy tumors by agonistic CD40 antibody monotherapy." (PMID 38008741, 2023). "The CD40/CD40L engagement is being exploited in cancer therapy and several anti-CD40 antibodies have been developed and tested in clinical trials." (PMID 37108657, 2023). "In summary, we have shown for the first time that PIP increases the sensitivity of BC cells to apoptosis induced by anti-cancer drugs, which is associated with overexpression of specific pro-apoptotic genes (CRADD, DAPK1, FASLG, CD40, and BNIP2)." (PMID 37085653, 2023). "Results from such investigations will provide the foundation for the development of combination therapies using agonist anti-CD40 monoclonal antibodies in cancer treatment." (PMID 36823405, 2023). "The use of an immunogenic smart radiotherapy biomaterial (iSRB) for the delivery of anti-CD40 is effective in treating different cancers in animal models." (PMID 38140118, 2023). "As a result, repolarizing of procancerous TAMs into cancer-fighting macrophages, for example, by agonistic anti-CD40 antibodies, presents a promising therapeutic avenue." (PMID 38060331, 2023). "Here, we demonstrate that the inhibition of LDHA and GLS1—two metabolic targets that are currently under investigations in clinical trials for cancer therapy—impairs anti-CD40 monoclonal antibody-induced antitumor responses." (PMID 36823405, 2023). "Further, combination based approaches with immuno-oncology agents informed by enhanced understanding the mechanisms of targeted approaches, including CD40 agonism, have the potential to further improve cancer outcomes." (PMID 37304285, 2023). "The consequence of CD40 activation in cancer cells include induction of ROS (reactive oxygen species), activation of ASK1/p38/JNK pathway, and the regulation of the transcription of the pro-apoptotic mitochondrial proteins such as Bak and Bax68." (PMID 37085653, 2023). "Since such inert biomaterials are already being used clinically, the use of iSRBs, which can perform the function of fiducials but also deliver drugs like anti-CD40, presents an excellent opportunity for research and development in cancer treatment." (PMID 38140118, 2023).
cancer (continued). "Similar to Toll-like receptors (TLRs), the CD40 pathway acts as a linkage between DCs and adaptive immunity in cancer." (PMID 37444617, 2023). "In contrast, CD40 targeting therapies are being employed in cancer because of its role in activation and maturation of DCs." (PMID 37435963, 2023). "Other immunotherapeutic approaches investigated for PDAC include cancer vaccines, CD40 agonists, chimeric antigen receptor (CAR), T cell therapy and oncolytic viruses." (PMID 37240052, 2023). "CD40 agonist antibodies have been shown to make a difference in the clinical treatment of different cancers and are closely related to B cells." (PMID 36890557, 2023). "Among these therapies are immune checkpoint inhibitors, cancer vaccines, CD40 agonists, chimeric antigen receptor (CAR) T cells and oncolytic viruses." (PMID 37240052, 2023). "The CD40 pathway and its activation can exert different roles in cancer, where it can lead to apoptotic or pro-survival effects." (PMID 37970926, 2023). "The degree of methylation of PIK3R5, PIK3R1, MAPK10, and CD40 genes in cancer tissues was significantly increased compared to normal tissue, while most of the remaining genes were reduced." (PMID 37666853, 2023). "The contingency table points to significant differences between CD40 and patient's age and cancer type and staging." (PMID 37970926, 2023). "Overwhelming evidence demonstrates that agonistic CD40 antibodies expand cancer antigen-specific CD8+ T cells and provide robust immune protection by cross-presenting DCs." (PMID 38008741, 2023). "Targeting CD40 by agonistic antibodies used as vaccine adjuvants or for cancer immunotherapy is a strategy to stimulate immune responses." (PMID 37353664, 2023). "Co-incubation of bone marrow-derived dendritic cells (BMDC) with ML162, RSL-3 and Erastin-induced ferroptotic cancer cells cause increased exposure of CD86, CD40, and MHCIIhigh indicative for strong DC maturation." (PMID 35760796, 2022). "Another study tested B cells as a cancer vaccine, using CD40-activated B cells in combination with chemotherapy in dogs with non-Hodgkin’s lymphoma." (PMID 36159874, 2022). "Expansion of DC development in combination with TLR ligands or CD40 agonists has been shown to be applicable in cancer therapy in mouse models." (PMID 34413487, 2022). "Motivated by promising results in a variety of cancer animal models, several human CD40 mAbs have been developed and evaluated in clinical trials over the last two decades." (PMID 35911742, 2022). "Together, these studies demonstrate the prospect of using a CD40 agonist strategy in patients for cancer therapy." (PMID 35935985, 2022). "A more direct role of CD154 in cancer regulation is represented by its capacity to halt growth or induce apoptosis of malignant cells via its interaction with CD40 on their surface." (PMID 35681441, 2022). "SEA-CD40 is a humanized IgG1 CD40 agonist antibody which binds to APCs, induces enhanced crosslinking through FcγRIIIa, and can augment NK-cell binding to cancer cells." (PMID 36077755, 2022). "Overall, the scattered successes in cancer therapy of different patients leave undiscovered the biological reasons that must be explored to exploit the CD40 agonist as monotherapy or in combination with other ICIs." (PMID 35664746, 2022). "CD40 antibodies with various formulations have shown tolerable and feasible effects in patients with mesothelioma, pancreatic cancer, and other cancer types, when combined with chemotherapy." (PMID 35715855, 2022). "Since this initial proof-of-principle study, numerous studies have shown that CD40-specific antibodies can provide a platform for peptide or whole protein-based cancer vaccines." (PMID 34282297, 2022).